CCND3 (cyclin D3)
Diseases named in the same sentence as CCND3 in open-access papers (continued):
Sharing a sentence is not in itself a finding about the gene and the disease.
melanoma (17 papers, 2012 to 2024). A malignant, usually aggressive tumor composed of atypical, neoplastic melanocytes. "We found an increased expression of a CCND3 variant with a domain gain in the N-terminal region in melanomas." (PMID 34281234, 2021). "The expression of cyclin D3 in melanoma cells is associated with regulation of the cell cycle at the G1-S phase, which is necessary for efficient entry into S phase, increased cell proliferation, and is a poor prognostic factor." (PMID 29214525, 2017). "CCND3 is a biomarker component of differentially expressed mRNA signature in melanoma respect to normal tissues, and is related to survival outcomes in triple negative breast cancer patients." (PMID 38755629, 2024). "Our study shows that SOX10-deficient melanoma cells are slow-cycling, which is an effect associated with reduced expression of MITF and cyclin D3 as well as enhanced p21Cip1." (PMID 35296667, 2022). "Downregulation of the E2F family of transcription factors except E2F6 was reported in studied malignant melanoma cell lines along with a time-dependent decrease in cyclin A, cyclin D3, cyclin E, cdk2, cdk4, and cdc2 expressions." (PMID 36362950, 2022). "The contribution of cyclin D3 to FER regulation of melanoma cell proliferation remains an important area for future investigation." (PMID 30909648, 2019). "Cyclin D3 is overexpressed in melanoma cells relative to normal melanocytes, and it is necessary for G1 to S-phase progression." (PMID 30909648, 2019). "According to the literature, the level of cyclin D3 is significantly higher in melanoma than in dysplastic nevi." (PMID 29214525, 2017). "In contrast, the melanoma samples used here show that cytoplasmic expression of BRMS1 is inversely associated with markers of proliferation, cyclin D3, cyclin A, Ki67, p21Waf1/Cip1." (PMID 22356677, 2012). "In addition, an earlier study found positive cyclin D1-nuclei staining in 0.34%, 5%, and 7.75% and positive cyclin D3-nuclei staining in 1.8%, 6.4%, and 17.8% in normal naevi, dysplastic naevi and melanoma biopsy sections, respectively." (PMID 23251804, 2012). "Additionally, previous studies reported that other genes are frequently mutated in melanoma and other cancer types, including BRCA2 (9/112, 8%), LRP1B (9/112, 8%), MET (8/112, 7%), PRKDC (7/112, 6%), NOTCH4 (7/112, 6%), CCND3 (6/112, 5%), and FGF3/4/19 (6/112, 5%)." (PMID 37649078, 2023). "Cyclin D3 (CCND3) is involved in the progression and proliferation of the G1-S cell cycle of melanoma cells and expressed in melanocytes." (PMID 38754841, 2024). "The greatest simultaneous decline of cyclin D1, CDK4 kinase, and cyclin D3 and CDK6 kinase was observed after treatment of melanoma cell with the combination of inhibitors: mTOR—everolimus, with ERK1/2 inhibitor—U126 or B-RAF-GDC-0879." (PMID 29214525, 2017). "Treatment of melanoma cells with inhibitor of ERK1/2 kinase—U126 and B-RAF-GDC-0879, resulted in the most profound reduction in expression of cyclin D1 and CDK4 kinase but only slightly affected the level of cyclin D3 and CDK6 kinase." (PMID 29214525, 2017). "In this paper, we could also show that, in BLM melanoma cells, ERβ agonists exert their antiproliferative activity through the modulation of cell cycle progressing factors (cyclin D1, cyclin D3, p27), without triggering the apoptosis pathway." (PMID 26225426, 2015). "Moreover, they reported that ERβ agonists exert antiproliferative activities in BLM melanoma cells by modulating cell cycle progressing factors (CCNB1, CCND3, and p27) and by blocking the G1-S transition phase without triggering the apoptosis pathway." (PMID 31696058, 2019).
lymphoma (16 papers, 2012 to 2025). A malignant (clonal) proliferation of B- lymphocytes or T- lymphocytes which involves the lymph nodes, bone marrow and/or extranodal sites. "Our outcomes suggested that elevated cyclin D3 level implicated an unfavorable OS in lymphoma (HR 3.72; 95% CI 2.18–6.36, p < 0.000)." (PMID 31198407, 2019). "And the results showed that higher cyclin D3 level implicated an unfavorable OS in lymphoma patients." (PMID 31198407, 2019). "In addition to lymphoid cancers, somatic mutations in CCND3 have recently been identified in bone tumours." (PMID 37510349, 2023). "Because overexpression of cyclin D3 or mutation of D3 at Thr283 is frequently observed in Burkitt’s lymphoma and leukemia and c-Myc driven murine lymphomas, we further defined whether Fbxl8 has tumor suppressive function in hematopoietic cells." (PMID 33122824, 2021). "Thus, either loss of Fbxl8 or gain of a cyclin D3 mutation that stabilizes cyclin D3 protein level will accelerate cell cycle progression and lymphoma cell growth consistent Fbxl8 functioning as a tumor suppressor." (PMID 33122824, 2021). "However, recent work revealed that cyclin D3 is mutated at Thr283 in 50% of Burkitt’s lymphomas supporting the importance of post-translational regulation of cyclin D3 with this residue Thr283 in lymphoma." (PMID 33122824, 2021). "Previous studies have shown that CNF2024 induced G2 cell cycle arrest in Hodgkin’s lymphoma cells and decreased cell cycle-related proteins, including CDK1, CDK2, and cyclin D3, along with either G1 or G2 cell cycle arrest in multiple lymphoma cell lines." (PMID 38794139, 2024). "In this regard, it is of interest that also in this disorder the clonally expanded rogue B-cells harbor mutations of lymphoma-related genes (CARD11, TNFAIP3, CCND3, ID3, BTG2, KLHL6)." (PMID 39055707, 2024). "Higher expression of cyclin D3 in various tumors including lymphoma is an unfavorable prognostic biomarker that affects the outcome of chemotherapy makers." (PMID 35897737, 2022). "Clinically, the expression of cyclin D3 is inversely correlated with the expression of Fbxl8 in lymphomas from human patients implicating Fbxl8 functions as a tumor suppressor." (PMID 33122824, 2021). "Normal lymph node tissues, spleen, tonsil, and lymphomas arrayed on slides (US Biomax, Inc.)were stained with cyclin D3 and Fbxl8 specific antibodies and IHC scores of each core were calculated." (PMID 33122824, 2021). "Together these results demonstrate that Fbxl8 functions as a tumor suppressor through degradation of cyclin D3 in lymphoma." (PMID 33122824, 2021). "Conversely, knockdown of Fbxl8 promoted lymphoma cell proliferation with upregulated cyclin D3 expression." (PMID 33122824, 2021). "Patient samples with low, medium, or high expression of cyclin D3 have high, medium, or low expression of Fbxl8, respectively, underscoring Fbxl8 negatively regulates cyclin D3 expression in human lymphomas in a dose dependent manner." (PMID 33122824, 2021). "In summary, Fbxl8 regulates cell cycle progression and lymphoma cell proliferation through cyclin D3." (PMID 33122824, 2021). "Expression of the several STAT3-controlled mediators of lymphoma cell proliferation and survival, including Bcl2l1, Bcl6, Casp3, Ccnd3, and Myc, was reduced." (PMID 29433938, 2018). "CC214-1 inhibited c-Myc, and cyclin D3 translation by decreasing polysomal fractions from lymphoma cells." (PMID 25839159, 2015). "CDK6 is the initial CDK induced during T-lymphocyte activation/proliferation and is highly expressed in T-cell lymphoblastic leukemias/lymphomas; similarly, over-expression of cyclin D3 is oncogenic in an array of mouse and human T-ALL cell lines." (PMID 22514694, 2012).
lymphoma (continued). "The transcription level of cyclin d3 (Ccnd3) was high, whereas the expression levels of cyclin d1 (Ccnd1) and d2 (Ccnd2) were quite low, presumably reflecting the characteristics of T lymphomas, such as Jurkat cells." (PMID 40734673, 2025). "Due to the expression profile of CCND3, it is no surprise that lymphoid cancers are most commonly associated with dysregulation of CCND3." (PMID 37510349, 2023). "This further suggested that cyclin D3-dependent kinase might be a novel therapeutic target in certain lymphomas that harbor low expression of Fbxl8 or high expression of cyclin D3." (PMID 33122824, 2021). "This supports the notion that Fbxl8-cyclin D3 axis might be a potential novel biomarker to predict the efficacy of CDK4/6i in lymphomas." (PMID 33122824, 2021). "Importantly, cyclin D3T283A, a non-phosphorylable mutant, rescued Fbxl8 overexpression mediated cell proliferation attenuation, indicating that Fbxl8-cyclin D3 axis plays a critical role in regulating lymphoma cell proliferation." (PMID 33122824, 2021). "We just discovered that high expressing cyclin D3 was related to decreased OS in lymphoma." (PMID 31198407, 2019). "We finally tested whether Fbxl8 reduces lymphoma proliferation through degradation of cyclin D3." (PMID 33122824, 2021). "Genes frequently mutated in BL are located in the BL-specific spot A (e.g. ID3, CCND3) and D (e.g. TCF3, SMARCA4, MYC) indicating their increased activity in BL and partly in intermediate lymphomas." (PMID 31039827, 2019). "FISH analyses using BAC clones covering lymphoma breakpoints (BCL2, BCL6, BCL11A, CCND1, CCND3, IG-H/K/L, JAK2, LMO2, MYC, PAX5, REL) all tested normal, excluding rearrangements at these loci." (PMID 26599546, 2015). "Immunoblot analysis of tumor extracts confirmed that cellular proteins that are highly expressed in GC B cells, including cyclin D3, GCSAM, TCL1, Myb, TCF3 and BACH2 are expressed at higher levels in the ΔEBNA2 + Myc lymphomas in comparison to the ΔEBNA2 alone lymphomas." (PMID 38620028, 2024). "We further used a recently developed online tool to assess the lymphoma patients’ overall survival with gene expression, and observed that the low expression of Fbxl8 mRNA significantly correlated with reduced overall survival for lymphoma patients while the expression of cyclin D3 mRNA does not." (PMID 33122824, 2021).
leukemia (14 papers, 2012 to 2025). A malignant (clonal) hematologic disorder, involving hematopoietic stem cells and characterized by the presence of primitive or atypical myeloid or lymphoid cells in the bone marrow and the blood. "It was found that our combination downregulated p27, cyclin D3 and CDK2, which agrees with previous reports showing that the decrease in Hsp90 is associated with the G1 arrest in leukemia cells." (PMID 32397330, 2020). "And abnormal Cyclin D3 was also found in other cancers, such as leukemia, HCC, gliomas, bladder carcinoma, prostate cancer and osteosaroma." (PMID 26412984, 2015). "mTORC1 signaling in leukemia cells regulates other growth and survival factors besides cyclin D3 and MCL-1; for example, knockdown or inhibition of mTORC1 in human T-ALL cells reduces expression of the oncoprotein c-MYC while increasing expression of the pro-apoptotic protein PUMA." (PMID 34408976, 2021). "On the other hand, cyclin D3 seems a promising marker in distinguishing SDRPL from other splenic B-cell lymphomas and leukaemias as it is reported to be exclusively expressed in approximately 70% of SDRPLs." (PMID 40282427, 2025). "For the leukemia dataset, among the 10 top-ranked genes, two genes (ZYX and CCND3) are cancer ones, five (APLP2, CD33, SP3, CD63, PSME1) and one other genes (CST3) are directly or indirectly associated with cancer genes, respectively." (PMID 22830977, 2012). "Employing the MAGeCK algorithm, this focused CRISPR screen unveiled COX4I1 (encoding Cytochrome c oxidase subunit 4 isoform 1) as a top essential gene in leukemia cells, alongside five previously reported leukemia essential genes (MYC, RPS6, CCND3, GAB2, and AURKB)." (PMID 39716856, 2025).
lung carcinoma (14 papers, 2014 to 2024). "Collectively, our findings reveal that ZNF652 exerts a tumor suppressor role in lung cancer by inducing cell cycle arrest and cellular senescence via transcriptionally downregulating cyclin D3." (PMID 39500884, 2024). "The Ki-67 and CCND3 expression level was lowest in the treadmill running+ZA group lung cancer cells in the tibia, which confirmed that in the treadmill running+ZA group, tumor growth in the tibia was suppressed most effectively." (PMID 38547196, 2024). "Further investigation unveiled that METTL1/WDR4 accelerated lung cancer cell proliferation and migration by enhancing tRNA m7G modification and oncogenic mRNA translation, particularly CCND3 and CCNE1, the cell-cycle regulators." (PMID 36733406, 2023). "Treatment of lung cancer cells with luteolin decreased the expression of cyclin D1 and cyclin D3, cell cycle markers compared with control." (PMID 33982869, 2021). "In the present study, DDA1 was shown to be responsible for lung cancer cell G1/S transition and cell proliferation through the regulation of cyclin D1, cyclin D3, cyclin E1 and cyclin B1 expression." (PMID 28211159, 2017). "In deed, the expression of cyclin D1, cyclin E2, and cyclin D3 were downregulated in CHRNA5 shRNA transfected lung cancer cells, suggesting that the G0/G1 phase to S phase transition might be regulated by α5-nAChR through cell cyclins." (PMID 28878681, 2017). "To gain first insights into the working mechanism of KJ-Pyr-9-induced survival decrease in MYC expressing lung cancer cells, we tested for alterations in mRNA levels of several known MYC target genes, such as CCND1, CCND3, and MYC itself." (PMID 33925297, 2021). "The fifth one is hsa-mir-195, which participates in the process of affecting lung cancer by regulating MYB, cyclin D3, Ailanthone." (PMID 32428028, 2020). "Among them, four genes involved in the GADD45 signaling pathway (CCNE2, CCND3, CDKN1A, and CCNB1), were reactivated by promoter DNA methylation in the GA-treated lung cancer H1299 cells." (PMID 29416619, 2018). "Additionally, the putative targets of miR-497-5p including PSMD7, CCND3, SMURF2, and WNT7A increase chemoresistance in gastric cancer, acute myeloid leukemia, lung cancer and OSCC, respectively." (PMID 36703917, 2022). "Cyclins are often upregulated in cancers; however, cyclin D1 has not been shown to be a negative prognostic factor in cancer, cyclin D2 is often methylated and thus downregulated in lung cancer, and cyclin D3 was suggested not to have a profound role in tumorigenesis." (PMID 25325012, 2014).
hepatocellular carcinoma (11 papers, 2012 to 2025). A malignant tumor that arises from hepatocytes. "In hepatocellular carcinoma, it acts directly on cyclin D3, causing cell cycle arrest and regulating the expression of SOX4, thereby controlling the growth of hepatocellular carcinoma." (PMID 38002064, 2023). "We restored miR-99a in 786–0 cells and found that the expression of p-p70S6K, p-4E-BP1, cyclin D1, cyclin D3 and cyclin E are really downregulated, consistent with the previous reports in hepatocellular carcinoma." (PMID 23173671, 2012). "Targeting Cyclin D3 by miR-138 could induce cell cycle arrest in hepatocellular carcinoma." (PMID 26412984, 2015). "CHEK1, CDC25A, and CCNE1, together with CCND1, CCND3, CDK4, CDK6, BTRC, E2F3, and FOXK1, were previously identified as the targets of miR‐497∼195 cluster in hepatocellular carcinoma." (PMID 40548926, 2025). "miR‐138 is significantly downregulated in anaplastic thyroid carcinoma (ATC), where it regulates cyclin D3 (CCND3), as well as in hepatocellular carcinoma (HCC), where it regulates the human telomerase reverse transcriptase (hTERT)." (PMID 30719845, 2019).
ovarian carcinoma (11 papers, 2009 to 2020). A malignant neoplasm originating from the surface ovarian epithelium. "As a result, Mirk kinase inhibition stabilizes cyclin D1 and cyclin D3 in ovarian cancer cells, as well as in several other types of cells." (PMID 25061503, 2014). "In the discovery set, SNPs in several genes were found to be associated with the risk of ovarian cancer; of these, five genes (ABL1, CCND3, CDKN1A, E2F3 and CDK2) were significant in log-additive models (P-value <0.05)." (PMID 19738611, 2009). "A previous studies in breast and ovarian cancer cells demonstrated that PEA3 controls the expression of cell cycle regulators such as Cyclin D3 and p21 respectively, and hence suggested that it might be involved in controlling proliferation." (PMID 21143918, 2010). "Our study highlights the capacity of XFC to specifically decrease Cdk4, Cyclin D3, and p27 expressions in chemoresistant SKOV-3 ovarian cancer cells." (PMID 31827554, 2019). "Interestingly, compared with parental cells, ovarian cancer cells resistant to flavopiridol and cisplatin showed the increased expressions of CDK1, cyclin D3 and Rb, decreased expressions of cyclin B, and equal expressions of cyclin A, cyclin E, CDK2, CDK4." (PMID 25962959, 2015). "Interestingly, although CCND2 and CCND3 are not overexpressed in human ovarian cancer, messenger RNA expression levels for both CCND2 and CCND3 were significantly upregulated in cancerous ovaries of laying hens." (PMID 23236518, 2012).
colon carcinoma (10 papers, 2005 to 2022). "To further analyse the effect of miR-142-3p and exosomes from BM-MSCs on Notch signal pathway in human colon cancer, we examined the expression of Numb and Notch target genes: Hes1, P21, and cyclin D3, by real-time PCR." (PMID 30220706, 2018). "There were also significant differences between rectal and colon cancers in gene amplification of all cyclins except cyclin D3, even when adjusted for gender, tumor differentiation grade, Dukes' tumor stage and age at surgery." (PMID 20029639, 2009). "In colon tumours, cyclin D1 was overexpressed in 44%, cyclin D2 was overexpressed in 53% and cyclin D3 was overexpressed in 35% of the cases." (PMID 16012517, 2005). "Finally, miR-4779 expression was low in 9 of 10 colon cancer tissues, whereas PAK2 and CCND3 expressions were significantly high in colon cancer tissues." (PMID 29362401, 2018). "There were highly significant differences between the rectal and the colon cancers in the protein expression of cyclin D1, cyclin D3, cyclin E, nuclear β-catenin, and c-Myc, even when adjusted for Dukes' stage, differentiation grade, gender, and age of patient at the time of surgery." (PMID 20029639, 2009). "Moreover, in cell lines derived from oral squamous cell carcinoma (HSC-2, HSC-3, and HSC-4) and colon carcinoma (DLD-1), α-mangostin induced G1 arrest by downregulating CDK4, CDK2, cyclin D3, and cyclin E, as well as through the upregulation of the p27kip1 and p21waf1/cip1 CDK inhibitors." (PMID 34885809, 2021).